TAPBP (TAP binding protein)
Description:
Involved in the association of MHC class I with transporter associated with antigen processing (TAP) and in the assembly of MHC class I with peptide (peptide loading).
Synonyms: TPN; TPSN; NGS17; TAPA; MHC1D3
Tractability: Antibody: UniProt predicts a signal peptide or a membrane-spanning region; the Human Protein Atlas places it where antibodies can reach. PROTAC: ubiquitination databases record sites on it; its protein half-life has been measured.
Safety:
Unwanted effects reported when the protein is acted on. In parentheses: how it was acted on, where the effect was seen, and who reports it.
aspirin-induced decline in forced expiratory volume in 1 s (FEV1) (source: ClinPGx)
Gene: Protein-coding gene on chromosome 6 (33,299,694 to 33,314,284, reverse strand). Ensembl gene ENSG00000231925.
Subcellular location: Endoplasmic reticulum membrane
Subcellular location (Human Protein Atlas): Nucleoli; Plasma membrane; Mitochondria
Pathways (Reactome):
Immune System: Antigen Presentation: Folding, assembly and peptide loading of class I MHC; ER-Phagosome pathway
Gene Ontology:
Molecular function: molecular adaptor activity; protein binding; protein folding chaperone; TAP complex binding; TAP1 binding; TAP2 binding; MHC class I protein binding; MHC class I protein complex binding; peptide antigen binding
Biological process: MHC class Ib protein complex assembly; peptide antigen assembly with MHC class I protein complex; protein-containing complex assembly; regulation of gene expression; regulation of protein complex stability; peptide antigen stabilization; retrograde vesicle-mediated transport, Golgi to endoplasmic reticulum; antigen processing and presentation of endogenous peptide antigen via MHC class I; antigen processing and presentation of peptide antigen via MHC class I; protein folding
Cellular component: endoplasmic reticulum membrane; Golgi membrane; MHC class I peptide loading complex; Tapasin-ERp57 complex; endoplasmic reticulum; endoplasmic reticulum-Golgi intermediate compartment membrane; lumenal side of endoplasmic reticulum membrane; phagocytic vesicle membrane; membrane
Genetic constraint (gnomAD): Loss-of-function variants: 39 observed, 48.02 expected, observed/expected ratio (o/e) 0.81, 90% interval 0.63 to 1.06. The upper end of that interval is the gene's LOEUF score, 1.06, which puts it in group 4 of 6, group 1 being the genes least tolerant of losing a copy. Missense variants: 513 observed, 604.95 expected, observed/expected ratio (o/e) 0.85, 90% interval 0.79 to 0.91. Synonymous variants: 226 observed, 262.91 expected, observed/expected ratio (o/e) 0.86, 90% interval 0.77 to 0.96.
Gene-disease validity (ClinGen):
ClinGen rates the evidence that TAPBP causes each of these diseases.
MHC class I deficiency (autosomal recessive): Moderate.
Homologues: Orthologues: chimpanzee TAPBP (99% identical), macaque TAPBP (94% identical), rabbit TAPBP (86% identical), pig TAPBP (82% identical), dog TAPBP (79% identical), mouse Tapbp (75% identical), rat Tapbp (74% identical), guinea pig TAPBP (68% identical), zebrafish tapbp.1 (29% identical), zebrafish tapbp.2 (29% identical), tropical clawed frog tapbp (27% identical). Paralogues in human: TAPBPL (26% identical), NCR3LG1 (11% identical).
Diseases named in the same sentence as TAPBP in open-access papers:
TAPBP is named in the same sentence as 51 diseases in open-access papers, as found by Europe PMC text mining. Sharing a sentence is not in itself a finding about the gene and the disease. The quoted sentences say what the papers report.
melanoma (6 papers, 2021 to 2024). A malignant, usually aggressive tumor composed of atypical, neoplastic melanocytes. "Expression of TAP1, TAPBP, and B2M was higher in 5hmC-high melanoma samples than 5hmC-low samples, indicating a positive correlation between TET2 activity and MHC I antigen-presenting genes." (PMID 39388288, 2024). "Next, we obtained multiple human malignant melanoma and colon adenocarcinoma tissue samples and stained for 5hmC as a marker for TET2 activity and for the key MHC I antigen-presenting genes TAP1, TAPBP, and B2M." (PMID 39388288, 2024). "Here, we show that TET2 in B16-OVA melanoma tumor cells is important for expression of some MHC class I antigen presentation genes, including the key regulators TAP1 and TAPBP, which are regulated downstream of IFN-γ–induced signaling." (PMID 39388288, 2024). "Collectively, these data highlight the therapeutic value of increasing the expression levels of TAP1, TAP2, TAPBP and PSMB9 in melanoma." (PMID 36458012, 2022).
Bare lymphocyte syndrome type I (3 papers, 2020 to 2025). "Autosomal recessive mutations in TAP1, TAP2, TAPBP, or B2M, are associated with major histocompatibility complex (MHC) class I deficiency." (PMID 41298860, 2025). "One disease, Bare lymphocyte syndrome type I, has a full intersection with the TAP complex, because three proteins (TAP1, TAP2 and TAPBP) are the proteins causing the disease and the members of the PC at the same time." (PMID 32591566, 2020).
colorectal cancer (3 papers, 2013 to 2022). A primary or metastatic malignant neoplasm that affects the colon or rectum. "Previous studies have identified associations between variation in or near TAPBP with clearance of hepatitis C (rs2071888) and survival in colorectal cancer (rs3106189)." (PMID 35858344, 2022). "While a reduction in TAPBP expression has been associated to tumor progression in colorectal cancer and chronic hepatitis B, the rs2071888 SNP has been associated with wild type gastrointestinal tumors and gallbladder cancer." (PMID 36233078, 2022).
lung carcinoma (3 papers, 2013 to 2022). "The ex vivo introduction of TAPBP expression in a murine lung carcinoma model increased surface MHC class I and restored susceptibility of tumor cells to antigen-specific cytotoxic T lymphocytes (CTL) killing." (PMID 23940558, 2013).
Obesity (3 papers, 2020 to 2023). Accumulation of substantial excess body fat. "TAPBP is linked to both mood disorders and obesity through the JNK pathway." (PMID 32942585, 2020). "Pathway analysis interaction for TAPBP, BDNF, and SORBS2 confirmed the relation of these genes in both obesity and mood disorders." (PMID 32942585, 2020). "The important role of TAPBP is not recognized in the past in both obesity and mood disorders, and just in recent years." (PMID 32942585, 2020). "As the results of gene enrichment pathways analysis exhibited that TAPBP, BDNF, and SRBP2 are related together by inflammatory pathways, we hypothesis that hypermethylation in these genes might play a crucial role in the co-occurrence of obesity and mood disorders due to the inflammation process." (PMID 32942585, 2020).
malaria (2 papers, 2022 to 2025). Malaria is a serious and sometimes fatal disease caused by a parasite that commonly infects a certain type of mosquito which feeds on humans. "Among those with tapasin-dependent allotypes, higher TAPBP i-expression levels (compared to lower) associated with protection against both parasitemia and clinical malaria to an extent that is equivalent to having tapasin-independent allotypes (regardless of TAPBP mRNA i-expression levels)." (PMID 35858344, 2022). "We next sought to determine whether TAPBP mRNA expression levels are associated with blood-stage P. falciparum infection and/or clinical malaria among Ugandan individuals enrolled in a large malaria cohort study." (PMID 35858344, 2022). "Among the more tapasin-dependent HLA-I allotypes, TAPBP mRNA i-expression levels associate with malaria disease outcomes, providing insight into the growing body of work on the genetic regulation of HLA-I–mediated antigen presentation and malaria-specific immune responses." (PMID 35858344, 2022). "High TAPBP mRNA i-expression levels, particularly based on the rs59097151 genotype alone or the combined rs111686073/rs59097151 genotype, associated with protection against both malaria incidence and parasite prevalence most strongly and consistently within the tapasin-dependent allotype groupings." (PMID 35858344, 2022).
ovarian carcinoma (2 papers, 2017 to 2024). A malignant neoplasm originating from the surface ovarian epithelium. "The levels of expression of antigen expression genes TAP1, TAPBP, B2M, and HLA-A (the human ortholog of the mouse H2-D1 gene) were shown to predict longer patient survival in colon and ovarian cancers." (PMID 39388288, 2024).
prostate carcinoma (2 papers, 2018 to 2025). A carcinoma that arises from epithelial cells of the prostate gland. "Nevertheless, through Mendelian randomization analysis based on GWAS data, our study found an association between TAPBP and prostate cancer." (PMID 41270069, 2025). "After combining single-cell sequencing, Mendelian randomization, and Bayesian co-localization analyses, we identified 1 gene (TAPBP) that is strongly associated with prostate cancer." (PMID 41270069, 2025). "The significant DMR identified with eight DMCs located in the TAPBP promoter further supported its role in prostate cancer." (PMID 29692867, 2018). "Our findings suggest that TAPBP is involved in the immune response and antigen presentation in prostate cancer, and it is negatively correlated with the occurrence of prostate cancer and adverse clinical features (such as higher PSA levels, higher malignancy, tumor metastasis, etc.)." (PMID 41270069, 2025). "This indicates that methylation of TAPBP might be a mechanism by which prostate cancer cells escape the immune surveillance and provide an appropriate microenvironment for tumor aggressiveness, allowing prostatic cancer cells’ transfer, spread, and growth." (PMID 29692867, 2018).
tuberculosis (2 papers, 2025). A chronic, recurrent infection caused by the bacterium Mycobacterium tuberculosis. "The results showed that PLTP, RNASEL, SEMA7A, and TAPBP were upregulated in the whole blood of tuberculosis patients, while NEDD4 and THBS1 were downregulated." (PMID 40182927, 2025). "In clinical samples from tuberculosis patients, the expression level of TAPBP is elevated, leading to enhanced antigen presentation and an increased proportion of CD8+ T cell immune infiltration." (PMID 40182927, 2025). "The discovery of these six mRNAs (NEDD4, PLTP, RNASEL, SEMA7A, TAPBP, and THBS1) not only reveals critical molecular mechanisms underlying immune regulation in tuberculosis but also establishes a robust theoretical foundation for advancing diagnostic and therapeutic strategies." (PMID 40182927, 2025). "NEDD4, PLTP, RNASEL, SEMA7A, TAPBP, and THBS1 were combined into a 6-mRNA feature panel for diagnosis of tuberculosis." (PMID 40182927, 2025).
viral infection (2 papers, 2018 to 2023). "The TAPBP and TAPBPR gene sequences have previously been described in trout where both genes were shown to respond to viral infection." (PMID 29471808, 2018).
atherosclerosis (1 paper, 2024). A disease characterized by the build-up of fatty material and calcium deposition in the arterial wall resulting in partial or complete occlusion of the arterial lumen. "Moreover, the STARNET study indicated that CD8+ T cells indirectly communicated with TAP2 through TAPBP and B2M, which suggested that there may be an immune system imbalance in the atherosclerosis process." (PMID 38720469, 2024).
biliary tract cancer (1 paper, 2022). "Compared with attezolzumab monotherapy for biliary tract cancer, TAPBP expression was higher in the combined treatment group (atezolizumab + MEK inhibitor)." (PMID 36311733, 2022). "Compared with atezolizumab monotherapy for biliary tract cancer, TAPBP expression was higher in the combined treatment group." (PMID 36311733, 2022).
breast carcinoma (1 paper, 2025). "In the context of breast cancer, BAP31 expression showed a positive correlation with TAPBP (r = 0.257, p = 6.55 × 10−18), HLA-A (r = 0.16, p = 9.81 × 10−8), and HLA-C (r = 0.146, p = 1.25 × 10−6)." (PMID 40649753, 2025).
bronchiectasis (1 paper, 2025). Segmental, irreversible dilation of the bronchial tree resulting in the accumulation of secretions which leads to obstruction. "We found that chronic necrotizing granulomatous skin lesions and childhood-onset bronchiectasis were common but not universal clinical features of TAP1, TAP2, TAPBP, and B2M deficiency." (PMID 41298860, 2025).
colon cancer (1 paper, 2017). "Methylation-specific PCR analysis of the TAPBP gene in the eight colon cancer cell lines investigated showed that it was partially methylated but unchanged by 5-AC treatment." (PMID 28622390, 2017). "All 8 colon cancer lines downregulated TAPBP compared to normal colon, but 6 of these cell lines showed a comparative upregulation when treated with 5-AC." (PMID 28622390, 2017).
cutaneous melanoma (1 paper, 2022). A primary melanoma arising from atypical melanocytes in the skin. "Notably, cg18930100 in TAPBP presented hypomethylation associated with both increased TAPBP RNA expression and increased patient survival in UV-mutant relative to non UV-mutant cutaneous melanoma patients." (PMID 35840550, 2022). "In addition to the findings focused on TAPBP, we reported that the UV mutational signature is associated with a high load (thousands) of epigenetic alterations affecting the methylome landscape of cutaneous melanoma." (PMID 35840550, 2022). "In complement with TAPBP, several HLA genes were also differentially methylated in UV-mutant versus non UV-mutant cutaneous melanoma in both BCH and TCGA, and these genes were centrally involved in the multiple immunological pathways identified." (PMID 35840550, 2022). "Methylation by pyrosequencing validated that obtained with the methylome-wide array, confirming the observed TAPBP hypomethylation (including similar effect sizes and baseline methylation levels) in UV-mutant relative to non UV-mutant cutaneous melanoma." (PMID 35840550, 2022). "All the significant correlations showed an inverse association between CpG methylation and RNA expression levels of each gene, with TAPBP showing hypomethylation while EIF2AK4 showing hypermethylation in UV-mutant relative to non UV-mutant cutaneous melanoma patients." (PMID 35840550, 2022).
intraepithelial neoplasia (1 paper, 2013). A precancerous neoplastic process that affects the squamous, glandular, or transitional cell epithelium without evidence of invasion. "Loss of TAPBP expression has been observed in 80% of high-grade intraepithelial neoplasia (HIN) compared with autologous colorectal mucosa, in 63% of primary adenocarcinomas in stage III and 79% of the matched lymph node metastases." (PMID 23940558, 2013).
membranous nephropathy (1 paper, 2023). "As potential therapeutic targets, CD151 and TAPBP could be examined for creating drugs that intervene in the progression and development of membranous nephropathy." (PMID 37974210, 2023).
osteosarcoma (1 paper, 2023). A usually aggressive malignant bone-forming mesenchymal neoplasm, predominantly affecting adolescents and young adults. "Furthermore, 49 (10.6%) tumors had LOH affecting APP gene(s) in the HLA region (TAP1/2, TAPBP, PSMB8/9, HSPA1A-L), including 14 (20.6%) osteosarcoma and five (22.7%) GBM cases with LOH in both TAP1 and TAP2." (PMID 38318504, 2023).
triple-negative breast carcinoma (1 paper, 2021). An invasive breast carcinoma which is negative for expression of estrogen receptor (ER), progesterone receptor (PR), and human epidermal growth factor receptor 2 (HER2). "In triple-negative breast cancer patients, down-regulation of CALR and TAPBP tend to indicate a poor prognosis.Previous studies have shown that the carcinogenic mechanism of CALR is related to the exposure of malignant primordial cells to CALR, HSP70 and HSP90 on the plasma membrane." (PMID 34910788, 2021).
tumor (25 papers, 2013 to 2025). "Downregulation of antigen-presenting MHC class I pathway in tumor cells was a common mechanism for tumor cells escaped from specific immune responses, which can be associated with coordinated silencing of antigen-presenting machinery genes, such as TAPBP." (PMID 29692867, 2018). "Moreover, we identified three differentially methylated regions within the MGRN1, MIR596, and TAPBP genes that have been linked to neuronal aging, tumor growth, and immune functions." (PMID 38414347, 2024). "VC enhanced the expression of MHC I antigen-presenting genes TAP1 and TAPBP in WT B16-OVA tumor cells." (PMID 39388288, 2024). "Pair Wilcoxon signed-rank test also suggested that the expression of TAPBP mRNA in tumor tissues was higher than in adjacent normal tissues (p<0.0001)." (PMID 36311733, 2022). "As an important biomarker, TAPBP from TIGS is an effective intrinsic tumor biomarker and can predict ICIs response in pan-cancers." (PMID 36311733, 2022). "The staining intensity score of TAPBP in tumor tissues was significantly higher than that in adjacent normal tissues." (PMID 36311733, 2022). "According to the TCGA-STAD cohort, it was found that the expression of TAPBP mRNA in tumor tissues was higher than that in normal tissues (Mann-Whitney U test, p<0.0001)." (PMID 36311733, 2022). "Our results showed that TAPBP promoter hypermethylation in the PPAT of obese PCa subjects likely reduced the expression or activity of TAPBP, downregulating tumor cell’s antigen presentation of immune cells in PPAT, leading to impaired CD8+ T cell activation." (PMID 29692867, 2018). "In contrast, ENHO exhibited negative co-expression with MHC class I-related genes (TAP1, TAP2, and TAPBP), which may reflect a tumor-driven mechanism aimed at evading cytotoxic T cell-mediated immune surveillance." (PMID 40647442, 2025). "Moreover, immunohistochemistry (IHC) was used to measure the expression of TAPBP protein in tumor tissues and adjacent normal tissues." (PMID 36311733, 2022). "The expression levels of B2M(p = 2.926e-05), HLA-C(p = 2.628e-03), HLA-E(p = 5.5166e-08), HLA-F(p = 9.376e-03), TAP1(p = 1.972e-09), TAP2(p = 1.245e-04) and TAPBP (p = 2.652e-12)in tumor tissues of dMMR patients were significantly higher than those of pMMR patients." (PMID 36527024, 2022). "In addition, the positive correlation between TAPBP expression and tumor microenvironment was confirmed by multi-color immunofluorescence staining, providing a clue for further study on the effect of TAPBP on ICB therapy." (PMID 36311733, 2022). "TAP1, TAP2, TAPBP, and β2-microglobulin (B2M) are critical proteins involved in the class I MHC antigen presentation process in virus-infected or tumor cells." (PMID 39388288, 2024). "Most MHC I molecules, including HLA-A, HLA-C, HLA-E, HLA-F, TAP1, TAP2, and TAPBP (all P < 0.05), were upregulated in PTPRD/PTPRT mutant patients, indicating enhanced anti-tumor immunity in PTPRD/PTPRT mutant patients." (PMID 36248841, 2022). "In order to study the molecular mechanism of CALR involved in tumor progression, we used String and GeneMANIA databases finding that PDIA3, B2M, GANAB, CANX, and TAPBP interact with CALR." (PMID 34910788, 2021). "The process of hiding the tumor identity involves major histocompatibility complex (MHC) I-related genes (e.g., HLA-A/B/C, TAP1/2, TAPBP, and B2M)." (PMID 31737562, 2019). "Further, we analyzed IRF8 target gene expression in GMPs, MDPs, and CDPs and found that, relative to controls, tumor-bearing mice had decreased mRNA expression of multiple MHC molecules, as well as TapBP, Tap2, Batf3, and Pml." (PMID 29593283, 2018). "Genes of the antigen-processing machinery and regulation (IRF1, IRF2, NF-κB1, NF-κB2, NLRC5, TAP1, TAP2, TAPBP) were not significantly expressed throughout all of the analyzed tumor transcriptomes." (PMID 35892842, 2022).